INS (insulin)
Diseases named in the same sentence as INS in open-access papers (continued):
Sharing a sentence is not in itself a finding about the gene and the disease.
Hyperglycemia (continued). "Diabetes mellitus is an heterogeneous group of disorders characterized by hyperglycemia due to an absolute or relative deficit in insulin production or action." (PMID 32698854, 2020). "Injection of C57BL/6 mice with multiple low doses of STZ resulted in hyperglycaemia and lower plasma insulin levels at 14 days after the first STZ administration." (PMID 32321922, 2020). "This can result in hyperglycemia, due to the overall lower amount of insulin circulating in the blood." (PMID 32983560, 2020). "The α-glucosidase inhibitors delay the digestion and absorption of carbohydrates, which suppresses postprandial hyperglycemia, while the biguanide drugs increase insulin sensitivity." (PMID 32847055, 2020). "It is difficult to assess which insulin-producing cell types are quantitatively contributing to the improvement of hyperglycemia." (PMID 32477262, 2020). "The subsequent step is decreased insulin secretion due to β-cell dysfunction and potential β-cell death, leading to hyperglycemia." (PMID 32775460, 2020). "Allicin was able to partially prevent the alterations in insulin signaling, which was traduced in reduction in hyperglycemia." (PMID 33203103, 2020). "The present investigation was undertaken to examine the role of additional insulin as well as maintained hyperglycaemia on carbohydrate metabolism at a low (40% VO2max) and high (70% VO2max) exercise intensity." (PMID 31707476, 2020). "Mean fasting blood serum glucose and insulin levels were within the normal range, with 1 and 21 patients who had hyperinsulinemia and hyperglycemia, respectively." (PMID 32481537, 2020). "Patients with DM display hyperglycemia induced by a damage in insulin secretion (type 1), insulin action (type 2), or both." (PMID 32733635, 2020). "Since Kuma mice treated with insulin implants showed a reversal of hyperglycemia, we then examined if the endogenous islets were affected using the pancreas dissected from Kuma mice treated with insulin implants for 4 weeks from 6-weeks of age." (PMID 32699230, 2020). "The loss of function mutations in SLC2A2 presumably leads to reduced function or expression of GLUT2 in the pancreatic β-cell impairing insulin secretion, leading to hyperglycemia." (PMID 32877990, 2020). "Hyperglycemia, insulin concentrations below 10% those of the controls, and glycosuria in all of the STZ-treated rats demonstrated that a single intraperitoneal injection of STZ can be used to create a suitable T1DM model." (PMID 33114049, 2020). "Infection incidence often brings prolonged hyperglycemia and frequent insulin injections in people with type 1 diabetes, which are significant anomalies." (PMID 32784179, 2020). "It is known that, through the insulin or oral anti-hyperglycemic agents, it is possible to control hyperglycemia, but diabetic patients develop long-term vascular complications (even after intensive glycemic control)." (PMID 31963760, 2020). "Skeletal muscles (SM) account for approximately 80% of total body glucose disposal in humans, and insulin resistance in SM manifests itself as impaired glucose uptake following ingestion of a carbohydrate meal that results in postprandial hyperglycemia." (PMID 33379327, 2020). "This disease is characterized by hyperglycemia resulting from defects in insulin secretion, insulin action, or both." (PMID 33062014, 2020). "The combined use of various drugs can play a role in regulating the body and has obvious therapeutic effects on stress hyperglycemia, lipid peroxide after abnormal glucose metabolism, and insulin-damaging hyperglycemia." (PMID 33062014, 2020). "We demonstrate the utility of this technology by inducing hyperglycemia in inducible insulin knockout mice (Ins1−/−;Ins2f/f)." (PMID 32601405, 2020).
Hyperglycemia (continued). "In contrast to alpha cells, in beta cells, mitochondria provide a decisive increase in ATP due to oxidation of glucose in mitochondria, which in the case of mitochondrial dysfunction leads to insulin dysregulation, especially in hyperglycemia." (PMID 33327428, 2020). "After 13 weeks feeding, the plasma glucose and insulin levels in the HF-0 group were significantly higher than those in the C-0 group, indicating that hyperglycemia and hyperinsulinemia were induced by HF diet as expected." (PMID 32801472, 2020). "It is a chronic systemic inflammatory disease characterized by hyperglycemia as a consequence of alterations in insulin secretion, in the action of insulin, or in both." (PMID 33260342, 2020). "Compared with the normal group, STZ induced hyperglycemia but led to decreased levels of serum insulin." (PMID 32020874, 2020). "As newly-synthesised insulin is preferentially secreted, hyperglycaemia simultaneously enhances de novo insulin biosynthesis in order for beta cells to replenish their insulin granule stores and, thus, retain their secretory competence." (PMID 32894308, 2020). "Beta cells often encounter ER overload due to increased metabolic demand, e.g., due to rapid and increased insulin biosynthesis and secretion in response to hyperglycemia to maintain beta cell physiology." (PMID 33158303, 2020). "Despite similar levels of hyperglycemia and similar daily insulin doses, only in progressors was activation of the NF-κB pathway observed, as indicated by the overexpression of TLR4, nuclear p65 and IL-6." (PMID 32116790, 2020). "We confirmed the development of INS resistance in NOD mice with severe hyperglycemia by observing minimal response to high doses of INS treatment." (PMID 32382087, 2020). "Insulin as well as oral medications has been used for the management of hyperglycemia in GDM patients." (PMID 33371325, 2020). "More recently, kaempferol has been proposed to improve hyperglycemia, glucose tolerance, and blood insulin levels and to preserve pancreatic beta-cell mass in obese diabetic mice." (PMID 32093050, 2020). "In an animal modelled study, it was highlighted that E2F1/E2F2 compound mutant mice have shown excessive polyuria, hyperglycaemia, and decline in blood insulin levels." (PMID 32884568, 2020). "The disease is mainly characterized as hyperglycemia, hypercholesterolemia and hypertriglyceridemia due to insulin secretion defects or reduced tissue sensitivity to insulin." (PMID 33118125, 2020). "For example, continuous hyperglycemia results in a decline in the mRNA levels of rat Cx36 (rCx36) in insulin-secreting cells in rats administered a continuous glucose infusion, an effect that is blocked by the inhibition of cAMP/PKA signaling." (PMID 33379194, 2020). "Lack of ATP will prevent the closure of ATP-sensitive K+ channels (that is required to activate insulin secretion), impair the steps of the secretion pathway that require energy, resulting in lower levels of the circulating hormone and hyperglycemia." (PMID 32528413, 2020). "This demonstrates that active fraction of alkaloids shows a hypoglycemic activity by mechanisms of insulin-releasing or insulin-mimicking action, thus ameliorating postprandial hyperglycemia." (PMID 32079131, 2020). "Leaf banaba extracts effectively control hyperglycemia and hyperinsulinemia by reducing blood glucose, insulin, TG, and glycated haemoglobin levels in diabetic mice." (PMID 32252239, 2020). "Currently, many studies have shown that alternative therapies can improve insulin secretion, hyperglycemia, and insulin sensitivity in animal models of T2D, in β-cell lines and in T1D." (PMID 33020399, 2020). "Insulin‐naïve patients with T2DM who had uncontrolled hyperglycaemia (HbA1c ≥7%) by OADs and were willing to initiate BI treatment were enrolled from 209 secondary and tertiary hospitals in eight geographical regions in China." (PMID 32318640, 2020).
Hyperglycemia (continued). "In patients with T2DM, hyperglycemia is primarily due to a decreased ability of insulin to inhibit hepatic glucose production and the impairment of glucose uptake by insulin-sensitive tissues." (PMID 32020874, 2020). "EMP treatment helped to maintain elevated plasmatic insulin in an attempt to control hyperglycemia in diabetic mice, up to 26 weeks of age." (PMID 32264944, 2020). "For this, a new special reimbursement scheme (SRS) for non-insulin medications used for treatment of hyperglycaemia in T2D was implemented in Finland on January 1, 2017." (PMID 33246453, 2020). "To study the chronic effect of hyperglycemia on the number of insulin and proglucagon positive-cells (bi-hormonal cells), we stimulated INS-1 cells with low-glucose (6 mM), basal glucose (11 mM) and high-glucose concentrations (20 mM) for 48 h." (PMID 33240888, 2020). "In type 2 diabetic individuals, excess lipid accumulation impairs peripheral insulin signaling in the liver and skeletal muscle which leads to dysregulated cellular lipid and glucose homeostasis and hyperglycemia." (PMID 32372975, 2020). "Among patients with hyperglycaemia, insulin was administered in the emergency room in 83.7% of cases." (PMID 32429960, 2020). "Other investigators have shown that even a single bout of low-intensity physical activity significantly reduces time in hyperglycemia and improves insulin sensitivity with a 1 day carryover effect." (PMID 32215273, 2020). "Apart from treating ischemia, MSCs have also been deemed successful in increasing insulin sensitivity as well as offering long-term hyperglycemia control." (PMID 33293476, 2020). "By maintaining euglycemia with the insulin clamp technique, skillfully performed in our laboratory, our study excluded confounding effects of hyperglycemia; thus, cardiac effects are exclusively attributed to insulin." (PMID 32308680, 2020). "The study found that with the same level of hyperglycemia, the fasting insulin levels in SDM rats was significantly increased, as was pancreatic β cell proliferation." (PMID 32647998, 2020). "Success in the alleviation of ER stress-induced hyperglycemia, restoration of insulin sensitivity, and fatty liver disease amelioration was observed upon TUDCA and 4-PBA treatments in obese mice." (PMID 33613564, 2020). "Based on human GWAS, SGCD, which is a component of the sarcoglycan complex, and JADE2, which acts as an E3 ubiquitin ligase, were suggested as candidate genes for impaired insulin secretion and hyperglycemia in the R2 congenic region (segment B)." (PMID 32703163, 2020). "Type 2 (T2) DM accounts for the majority of this increase and is characterized by hyperglycemia resulting from insufficient endogenous insulin secretion due to beta cell dysfunction or hyperinsulinemia and impaired tissue response to insulin." (PMID 33187118, 2020). "In vivo, Equol supplementation delayed the onset of the hyperglycemia and hyperlipemia, ameliorated insulin secretion failure, enhanced GSIS in isolated islets, and significantly reduced Chrebp and Txnip expression in islets." (PMID 31956333, 2020). "The accumulation of amylin in the pancreas can decrease the level of insulin, which will lead to disruptions in carbohydrate metabolism (hyperglycemia) and will promote the development of neurodegenerative disorders." (PMID 32503113, 2020). "T1DM usually develops early in patients’ lives (childhood or adolescence) and is classified as autoimmune disease with yet uncertain origin, resulting in systemic insulin deprivation, hyperglycaemia and a bias for the development of ketoacidosis." (PMID 32704554, 2020). "Hyperglycaemia is a metabolic condition resulting from defects in insulin secretion, insulin action, or both." (PMID 32855973, 2020). "When body has hyperglycemia, it leads to increase the association of Pdx1 with p300 HAT, which involved in the enhancement the histone acetylation and insulin transcription." (PMID 32815547, 2020).
Hyperglycemia (continued). "GDM is characterized by varying degrees of hyperglycemia due to the inability of pancreatic β-cells to adequately respond to the increased insulin requirements during the second and third trimester." (PMID 33287755, 2020). "After transplantation of insulin implants into female heterozygous Kuma mice at 8.5-weeks of age, hyperglycemia of the Kuma mice was rapidly normalized, sustained for 1 month." (PMID 32699230, 2020). "Consistent with their known impairment in pancreatic β-cell function, the KO mice demonstrated impaired insulin release at both time points, with corresponding hyperglycemia." (PMID 31918914, 2020). "As a consequence, increased pancreatic β cell death results in hyperglycemia, which is dependent on exogenous insulin administration, concomitantly with evident glucagon secretion imbalance." (PMID 32774865, 2020). "Hepatic vagal afferents reportedly act as a glucose sensor, as the mean rate of hepatic neural activity decreased following an injection of glucagon to induce hyperglycemia, but increased in response to insulin‐induced hypoglycemia." (PMID 32512650, 2020). "Ventricular delivery of NPY promotes insulin secretion and potentiates the insulinemic response to hyperglycemia, independently of food intake." (PMID 32405365, 2020). "The current study showed that babies with hyperglycaemia have significantly higher level of serum insulin more than the babies with normoglycaemia (36.0 versus 8.6μIU/ml)." (PMID 32637004, 2020). "Damages in functional islet mass, and correlated early-phase insulin secretion, was reported in CP patients with early development of postprandial hyperglycemia." (PMID 33250773, 2020). "This is the first description of an approved drug—identified by a repositioning—that promotes the generation of insulin-expressing cells from pancreatic ducts and ameliorates hyperglycemia in experimental type 1 diabetes." (PMID 32477262, 2020). "Since carbohydrate ingestion increases simultaneously, and proportionally, both plasma glucose and insulin levels, it is challenging to dissect the role of hyperglycemia vs. hyperinsulinemia on endothelial function." (PMID 32664350, 2020). "The hyperglycemia with high insulin accounted for a decrease of food intake in mammals after high-carbohydrate feeding." (PMID 32636801, 2020). "In conclusion, these results show that a short course of high-dose glucocorticoids in those with T2DM leads to hyperglycemia due to a significant decrease in insulin secretion." (PMID 32369480, 2020). "Rodent models of acute surgical injury and hemorrhage experience severe adrenergic stress and develop stress-induced metabolic derangements, including hyperglycemia and insulin resistance." (PMID 33097799, 2020). "Embedded in this modulation environment, pancreatic beta cells secrete the only hormone that lowers glucose in hyperglycemia (insulin, equimolarly with c peptide), and pancreatic alpha cells secrete a contra-regulatory hormone in hypoglycemia (glucagon)." (PMID 33510648, 2020). "The most common considerations PCP selected for insulin continuation or intensification were the degree of hyperglycemia/HbA1c levels (95.8%), patient compliance with existing regimen (80.3%), the risk of hypoglycemia (45.1%) and whether the patient was willing to increase insulin doses (36.6%)." (PMID 32957991, 2020). "It was found to produce normalization of fasting hyperglycemia and amelioration of excessive postprandial glucose excursions and increasing β-cell sensitivity, insulin secretion, and circulating insulin within seven days at a dose of 4 (mg/kg body weight/day)." (PMID 33255206, 2020). "In the Q141K+/+ mice, we observed significant hyperglycemia, significant increases in serum insulin, and IGF1, as well as increased fractional excretion of sodium." (PMID 32488095, 2020). "HFD-fed mice displayed impaired glucose tolerance and insulin action and hyperglycemia and hyperinsulinemia compared to LFD-fed mice (p < 0.001)." (PMID 33346251, 2020).
Hyperglycemia (continued). "MSC were reported to reverse hyperglycaemia in type 1 diabetic rodent models as they enhanced insulin secretion and modified the immunological niche within pancreatic tissue." (PMID 33239104, 2020). "Another experiment transplanting insulin implants into male heterozygous Kuma mice at 10-weeks of age also rescued the hyperglycemia." (PMID 32699230, 2020). "On the other hand, overexpression of TMBIM6 by adenoviral gene transfer reversed hyperglycemia in normal mice and in diet-induced obese mice which was partially explained by an increased insulin sensitivity and reduction of hepatic glucose production." (PMID 32394396, 2020). "Skeletal muscle is the primary insulin target tissue, and up to 75% of insulin-mediated glucose uptake occurs in the skeletal muscle at both euglycemia and hyperglycemia." (PMID 31952248, 2020). "One study used the VoiceDiab® app, which helps users calculate the bolus insulin needed to avoid hypo and hyperglycemia by entering blood glucose data (which can be voice-entered)." (PMID 32143452, 2020). "Loss of Ffar2 in mice increases the risk of diabetic status, since Ffar2 knockout (KO) mice exhibit fasting hyperglycemia, reduced insulin levels, and glucose intolerance, despite exhibiting normal insulin sensitivity." (PMID 32404878, 2020). "Mice with oxygen-induced retinopathy alone versus oxygen-induced retinopathy plus streptozotocin-induced hyperglycemia/hypoinsulinemia were assessed for glucose, insulin, IGF1, IGFBP1, and IGFBP3 in blood and liver." (PMID 33004691, 2020). "Our findings in the present study indicate that CLPr improves hyperglycemia during the lowered insulin sensitivity." (PMID 32801470, 2020). "A study by Sun Y et.al., were ghrelin gene was deleted in ob/ob mice showed a reduction in hyperglycemia and enhancement in glucose-induced insulin secretion." (PMID 32698854, 2020). "If the pancreatic beta cells are unable to secrete sufficient insulin to compensate for the reduced insulin sensitivity (termed beta cell dysfunction), hyperglycemia will ensue, leading to glucose intolerance and eventually T2DM." (PMID 32158768, 2020). "The impairment of β-cell function leads to under production of insulin, weakened glucose-stimulated insulin secretion, fasting hyperglycemia, and ultimately the development of type-2 DM." (PMID 33335883, 2020). "Apart from protein and omega-3 PUFA, taurine is reported to promote insulin release in pancreatic β-cells, reduce insulin and leptin resistances, and thus ameliorate hyperglycemia and dyslipidemia." (PMID 33322303, 2020). "We also show that overnight CR normalizes stress-induced hyperglycemia, while significantly decreasing insulin and glucagon production and increasing corticosterone and ketone body production." (PMID 33510613, 2020). "In patients with FBS, decreased uptake of glucose by the liver cells, leads to postprandial hyperglycemia, which is further exacerbated by low insulin secretion due to defective glucose sensing in the pancreatic ß cell." (PMID 33292488, 2020). "When prescribing insulin, close blood glucose monitoring is needed to try to avoid periods of hypoglycemia or hyperglycemia." (PMID 33371325, 2020). "Visceral fat accumulation can contribute to insulin resistance and hyperglycaemia, all measurable predictors of COVID-19 complications." (PMID 33267871, 2020). "Polyphenols decreased blood glucose in animals with hyperglycemia, protected β-cells against oxidative stress, limited apoptosis, and improved insulin action via changes in adiposity, gene expression, and enzymatic activity." (PMID 33255565, 2020). "This suggests that deficiency of TMEM16A facilitates glucose uptake and improves hyperglycemia, one of the main features of insulin‐resistant conditions." (PMID 32440483, 2020). "In the fed (postprandial) state, GLP-1 peptide has the ability to stimulate insulin secretion and the synthesis of glycogen in the liver, thus reducing postprandial hyperglycemia." (PMID 32121057, 2020).